SAMHD1 (SAM and HD domain containing deoxynucleoside triphosphate triphosphohydrolase 1)
Description:
Protein that acts both as a host restriction factor involved in defense response to virus and as a regulator of DNA end resection at stalled replication forks. Has deoxynucleoside triphosphate (dNTPase) activity, which is required to restrict infection by viruses, such as HIV-1: dNTPase activity reduces cellular dNTP levels to levels too low for retroviral reverse transcription to occur, blocking early-stage virus replication in dendritic and other myeloid cells. Likewise, suppresses LINE-1 retrotransposon activity. Not able to restrict infection by HIV-2 virus; because restriction activity is counteracted by HIV-2 viral protein Vpx. In addition to virus restriction, dNTPase activity acts as a regulator of DNA precursor pools by regulating dNTP pools. Phosphorylation at Thr-592 acts as a switch to control dNTPase-dependent and -independent functions: it inhibits dNTPase activity and ability to restrict infection by viruses, while it promotes DNA end resection at stalled replication forks. Functions during S phase at stalled DNA replication forks to promote the resection of gapped or reversed forks: acts by stimulating the exonuclease activity of MRE11, activating the ATR-CHK1 pathway and allowing the forks to restart replication. Its ability to promote degradation of nascent DNA at stalled replication forks is required to prevent induction of type I interferons, thereby preventing chronic inflammation. Ability to promote DNA end resection at stalled replication forks is independent of dNTPase activity. Enhances immunoglobulin hypermutation in B-lymphocytes by promoting transversion mutation (By similarity).
Synonyms: DCIP; MOP-5; hSAMHD1; SBBI88; Mg11; HDDC1; AGS5; CHBL2
Tractability: Small molecule: a structure with a bound ligand is known; it has a high-quality binding pocket. Antibody: its Gene Ontology location is reachable by antibodies, with high confidence. PROTAC: UniProt records ubiquitination sites on it; ubiquitination databases record sites on it; its protein half-life has been measured.
Target class: Enzyme; Hydrolase
Safety:
Unwanted effects reported when the protein is acted on. In parentheses: how it was acted on, where the effect was seen, and who reports it.
sensory neuropathy (source: ClinPGx)
Gene: Protein-coding gene on chromosome 20 (36,890,229 to 36,951,893, reverse strand). Ensembl gene ENSG00000101347.
Subcellular location: Nucleus; Chromosome
Subcellular location (Human Protein Atlas): Nucleoplasm; Plasma membrane
Pathways (Reactome):
Immune System: Interferon alpha/beta signaling
Metabolism: Nucleotide catabolism
Gene Ontology:
Molecular function: deoxynucleoside triphosphate hydrolase activity; dGTP binding; dGTPase activity; identical protein binding; nucleic acid binding; protein binding; RNA binding; RNA nuclease activity; single-stranded DNA binding; zinc ion binding; triphosphoric monoester hydrolase activity
Biological process: dATP catabolic process; defense response to virus; deoxyribonucleotide catabolic process; dGTP catabolic process; DNA damage response; DNA strand resection involved in replication fork processing; double-strand break repair via homologous recombination; negative regulation of type I interferon-mediated signaling pathway; protein homotetramerization; regulation of innate immune response; immune response; somatic hypermutation of immunoglobulin genes
Cellular component: chromosome; nucleoplasm; nucleus; site of double-strand break; tetraspanin-enriched microdomain
Genetic constraint (gnomAD): Loss-of-function variants: 31 observed, 47.08 expected, observed/expected ratio (o/e) 0.66, 90% interval 0.49 to 0.89. The upper end of that interval is the gene's LOEUF score, 0.89, which puts it in group 3 of 6, group 1 being the genes least tolerant of losing a copy. Missense variants: 486 observed, 586.98 expected, observed/expected ratio (o/e) 0.83, 90% interval 0.77 to 0.89. Synonymous variants: 185 observed, 203.88 expected, observed/expected ratio (o/e) 0.91, 90% interval 0.8 to 1.02.
Gene-disease validity (ClinGen):
ClinGen rates the evidence that SAMHD1 causes each of these diseases.
SAMHD1-related type 1 interferonopathy (autosomal recessive): Definitive. Any type 1 interferonopathies in which the cause of the disease is a variation in the SAMHD1 gene.
Homologues: Orthologues: chimpanzee SAMHD1 (99% identical), macaque SAMHD1 (94% identical), pig SAMHD1 (81% identical), dog SAMHD1 (78% identical), rabbit SAMHD1 (76% identical), mouse Samhd1 (73% identical), rat Samhd1 (72% identical), guinea pig SAMHD1 (67% identical), tropical clawed frog samhd1 (61% identical), zebrafish samhd1 (60% identical), Caenorhabditis elegans sahd-1 (27% identical), Drosophila melanogaster fal (16% identical).
Diseases named in the same sentence as SAMHD1 in open-access papers:
SAMHD1 is named in the same sentence as 174 diseases in open-access papers, as found by Europe PMC text mining. Sharing a sentence is not in itself a finding about the gene and the disease. The quoted sentences say what the papers report.
HIV-1 infection (147 papers, 2011 to 2026). The type species of lentivirus and the etiologic agent of acquired immunodeficiency syndrome (AIDS). "Our results provide new insights into the mechanisms underlying the apoptotic function of SAMHD1 during HIV-1 infection." (PMID 40434097, 2025). "In agreement with our U937 cells expressing the different SAMHD1 variants for residue K580, we found that transdifferentiated BLaER1 cells expressing SAMHD1-K580Q lose the ability to block HIV-1 infection when compared to WT BLaER1 cells." (PMID 39162568, 2024). "SAMHD1 K580 point mutations join a growing number of SAMHD1 mutations, including T592D/E, H376A, Q548A, and A525T, that are able to reduce dNTP levels but lose their ability to prevent HIV-1 infection." (PMID 39162568, 2024). "The SAMHD1 variants K580A and K580E were also unable to block HIV-1 infection, indicating that preventing acetylation at K580 disrupts the ability of SAMHD1 to block HIV-1 infection." (PMID 39162568, 2024). "We report BLaER1 cells as a novel human macrophage HIV-1 infection model combined with CRISPR/Cas9 knock-in (KI) introducing specific mutations into the SAMHD1 locus to study mutations in a physiological context." (PMID 37800914, 2023). "SPHK-mediated inhibition appears to reduce susceptibility to HIV-1 infection mainly by downregulating phosphorylation of SAMHD1, the inactive state of the innate HIV-1 restriction factor." (PMID 35412343, 2022). "In contrast, under the same infection conditions, microglia were highly susceptible to HIV-1 infection, despite the levels of endogenous SAMHD1, compared to other macrophage populations." (PMID 34440127, 2021). "The S93A mutation significantly impaired the ability of SAMHD1 to restrict HIV-1 replication in this single-round HIV-1 infection model." (PMID 33391506, 2021). "Primary monocyte-derived macrophages (MDMs) are susceptible to HIV-1 infection, and its replication capacity is dependent on SAMHD1 expression." (PMID 32197329, 2020). "Compared to activated CD4+ T cells, both macrophages and DCs are less susceptible to HIV-1 infection, largely due to high expression of the restriction factor SAMHD1." (PMID 31968566, 2020). "CD81 is associated with SAMHD1, decreasing its activity, increasing the availability of dNTP, and thus enhancing HIV-1 infection." (PMID 31708924, 2019). "SAMHD1 inactivation also clearly plays a role in IL-7-treated resting T cells, which are more susceptible to HIV-1 infection." (PMID 31042779, 2019). "The results show that the susceptibility of MDMs to HIV-1 infection can be affected by stimuli that alter the phosphorylation state of SAMHD1, one of which is the DNA damage response." (PMID 29515139, 2018). "AGS patients with SAMHD1 mutations can present with signs of lupus erythematosus, with many symptoms mimicking those of HIV-1 infection." (PMID 29176984, 2017). "Undifferentiated THP-1 cells have been reported to be susceptible to HIV-1 infection in part because SAMHD1 is in a phosphorylated restriction inactive form." (PMID 29301198, 2017). "We have identified cyclin D2 as the key step controlling susceptibility to HIV-1 infection by modulation of the signaling pathway leading to SAMHD1 phosphorylation." (PMID 27541004, 2016). "Macrophages are a heterogeneous cell population strongly influenced by differentiation stimuli that become susceptible to HIV-1 infection after inactivation of the restriction factor SAMHD1 by cyclin-dependent kinases (CDK)." (PMID 27541004, 2016). "Several studies suggested that SAMHD1-deficient cells produce elevated levels of type I interferons (IFNs) in response to HIV-1 infection." (PMID 27477283, 2016). "This study shows that differentiation stimuli strongly influence macrophage cell cycle and proliferation characteristics as well as susceptibility to HIV-1 infection through modulation of SAMHD1 activation." (PMID 27541004, 2016).
HIV-1 infection (continued). "Macrophages, as well as other myeloid lineage cells, become susceptible to HIV-1 infection after degradation or inactivation of the restriction factor SAMHD1, a triphosphohydrolase enzyme that controls the intracellular level of dNTPs." (PMID 27541004, 2016). "This difference in susceptibility to HIV-1 infection has been linked to the expression in myeloid cell types of the Vpx-interacting protein SAMHD1." (PMID 24805990, 2014). "siRNA knock-down of SAMHD1 in bone marrow-derived macrophages increased their susceptibility to HIV-1 infection." (PMID 24586870, 2014). "For this purpose, we stably expressed the indicated SAMHD1 variants in human monocytic U937 cells, and tested them for the ability to block HIV-1 infection." (PMID 24219908, 2013). "Remarkably, SAMHD1 variants that lost dGTP-dependent tetramerization potently restricted HIV-1 infection." (PMID 24219908, 2013). "We found that SAMHD1 variants that are defective for dGTP-dependent tetramerization potently blocked HIV-1 infection when compared to wild type SAMHD1, which suggested that oligomerization is not required for the antiretroviral properties of SAMHD1." (PMID 24219908, 2013). "Vpx has been shown to render monocytic cells permissive to HIV-1 infection by binding to and causing the proteosomal degradation of SAMHD1." (PMID 23092512, 2012). "We also found that unstimulated primary peripheral blood mononuclear cells (PBMC) from two AGS patients lacking endogenous SAMHD1 can support viral replication whereas cells from healthy donors encoding wild-type (WT) SAMHD1 were resistant to HIV-1 infection." (PMID 22174685, 2011). "However, these cells are also less susceptible to HIV-1 infection than active lymphocytes due to the presence of restriction factors such as SAMHD1 and a lower amount of dNTPs, as previously reported." (PMID 39623137, 2025). "In agreement, gene editing of K580 in the human BLaER1 cell line showed that an endogenously expressed SAMHD1 bearing the K580Q change was unable to block HIV-1 infection demonstrating that mutations in K580 are detrimental to the ability of SAMHD1 to block HIV-1 infection." (PMID 39162568, 2024). "To investigate whether the ability of Vpx to enhance innate immune activation during HIV-1 infection was linked to SAMHD1, we assayed infection and ISG induction in SAMHD1 KO cells." (PMID 33563288, 2021). "Interestingly, TRAF6 knockdown in SAMHD1-deficient cells significantly inhibited HIV-1 infection and activation of NF-κB induced by virus infection." (PMID 33177202, 2021). "Since MDMGs were differentiated from peripheral blood monocytes in GM-CSF- and IL-34-containing media, and GM-CSF has been shown to alter the phosphorylation status of SAMHD1 and render MDMs less susceptible to HIV-1 infection, we sought to determine the phosphorylation status of SAMHD1 in MDMGs." (PMID 33298546, 2020). "Interestingly, these varying levels of SAMHD1 T592 phosphorylation in different donors correlated with susceptibility to HIV-1 infection." (PMID 29884836, 2018). "If the block in HIV-1 infection induced by AhR activation in macrophages was primarily caused by SAMHD1 dephosphorylation and consequent dNTP depletion, we reasoned that infection in the presence of Vpx should reduce or abolish the inhibitory effect of AhR activation." (PMID 30132758, 2018). "To test whether UV light induced DNA damage would also cause a SAMHD1-mediated block to HIV-1 infection, we repeated the analysis substituting NCS treatment with UV irradiation." (PMID 29515139, 2018). "Monocyte derived macrophages (MDMs) express CD4 and CCR5, rendering them susceptible to virus entry but also express the myeloid restriction factor sterile alpha motif domain and HD domain-containing protein 1 (SAMHD1) that reduces their susceptibility to HIV-1 infection." (PMID 29515139, 2018). "We found aberrant alterations in SAMHD1 in HIV-1 target cells that could be explained by the immune activation caused by HIV-1 infection." (PMID 27922067, 2016).
HIV-1 infection (continued). "Therefore, SAMHD1 in SAMHD1+ CD4+ T cells became susceptible to SIV-Vpx mediated degradation during chronic HIV-1 infection." (PMID 27922067, 2016). "We also tested the ability of the different SAMHD1 variants to block HIV-1 infection." (PMID 27511536, 2016). "Interestingly, CD14+ cells from AGS patients with mutations in SAMHD1 are more susceptible to HIV-1 infection than cells from healthy controls." (PMID 24782834, 2014). "Remarkably, oligomerization-deficient SAMHD1 variants potently restricted HIV-1 infection." (PMID 24219908, 2013). "Genetic analysis of the SAMHD1 gene polymorphisms has been applied to determine whether the expression of SAMHD1 mRNA is affected by single nucleotide polymorphisms (SNPs) in SAMHD1 and whether the SNPs are associated with HIV-1 infection status." (PMID 24523981, 2013). "To understand whether dGTP-dependent tetramerization contributes to the antiretroviral properties of SAMHD1, we tested the ability of dGTP-dependent tetramerization-defective SAMHD1 variants to restrict HIV-1 infection." (PMID 24219908, 2013). "In addition, monocytes from AGS patients are highly susceptible to HIV-1 infection, and mutations that block hydrolase activity result in the loss of SAMHD1 antiviral activity." (PMID 24167505, 2013). "However, compared to full-length SAMHD1, these splice variants lack metabolic stability and catalytic activity to block HIV-1 infection." (PMID 24523981, 2013). "If this hypothesis is correct, HIV-2 strains that are associated with high viral load and AIDS (similarly to most HIV-1 infections) should show a reduced capability to infect myeloid cells and thus lack a potent SAMHD1 antagonist (like HIV-1)." (PMID 23497283, 2013). "However, there is a lack of clinical studies in this direction, and consequently a direct association between SAMHD1 and HIV-1 infection remains to be established." (PMID 24167505, 2013). "Moreover, VLP-Vpx treatment of SAMHD1-deficient resting CD4+ T-cells cannot further enhance HIV-1 infection, indicating that SAMHD1 is necessary for Vpx to relieve HIV-1 restriction in resting CD4+ T-cells." (PMID 23092163, 2012). "The findings demonstrate that MDM susceptibility to HIV-1 can vary depending on the phosphorylation state of SAMHD1 raising the possibility that it may be possible to regulate the susceptibility of cells to HIV-1 infection by increasing the antiviral activity of SAMHD1." (PMID 29515139, 2018). "Thus, differences on cell cycle regulation between M-CSF and GM-CSF macrophages also determined the susceptibility to HIV-1 infection and this may be a direct consequence of the control of the restriction factor SAMHD1 by CDK-mediated phosphorylation." (PMID 27541004, 2016). "SAM domain and HD domain-containing protein 1 (SAMHD1), the product of a gene linked to a rare and severe inherited autoimmune disease named Aicardi-Goutières syndrome, has recently been identified as the cellular factor that prevents HIV-1 infection in dendritic cells and macrophages." (PMID 23497283, 2013). "In vitro, fingolimod decreases HIV-1 infection and viral reservoir (VR) through SAMHD1 phosphorylation inhibition and reducing lymphocyte activation and CD4 expression." (PMID 42234672, 2026). "In summary, we demonstrated that endogenous SAMHD1 enhances apoptosis induced by HIV-1 infection through the mitochondrial pathway in monocytic cells." (PMID 40434097, 2025). "THP-1 Ctrl cells showed enhanced cleavage of caspases 3/7 and PARP upon HIV-1 infection compared to SAMHD1 KO cells at 1–4 dpi." (PMID 40434097, 2025). "Together, these results suggest that endogenous SAMHD1 enhances apoptosis induced by single-cycle HIV-1 infection in THP-1 cells." (PMID 40434097, 2025). "Some of the effects observed were modest compared to previous studies, which counteracted SAMHD1 restriction to achieve high HIV-1 infection rates in primary cells." (PMID 41354661, 2025).